TRAP1 (TNF receptor associated protein 1)
Diseases named in the same sentence as TRAP1 in open-access papers (continued):
Sharing a sentence is not in itself a finding about the gene and the disease.
tumor (continued). "TRAP1 is involved in TNF receptor-mediated signal transduction, and overexpression of TRAP1 decreases the production of reactive oxygen species, which accelerates the proliferation of tumor cells." (PMID 34786435, 2021). "TRAP1 not only regulated tumor metabolism through mitochondria, but also regulated glutamate metabolism, which plays an important role in tumor therapy." (PMID 34906113, 2021). "As previously reported in tumor models, TRAP1 inhibits SDH activity during early Zebrafish development, crucially contributing to a bioenergetic phenotype characterized by low levels of OXPHOS." (PMID 33934112, 2021). "In the present study, we demonstrate that the mitochondrial chaperone TRAP1 is a transcriptional target of HIF1α and that TRAP1 is induced in hypoxic conditions both in fish embryos and in tumor models." (PMID 33934112, 2021). "The rationale is that inhibition of TRAP1 would decrease the tumor ability to inhibit apoptosis, tumor resistance to oxidative stress and mitochondrial dysfunction." (PMID 34829705, 2021). "One study found that cells overexpressing TRAP1 had enhanced proliferative potential compared to TRAP1 knockdown cells, along with increased tumor metastasis in vivo." (PMID 34831420, 2021). "TRAP1 silencing also leads to increased activity of the complex IV and ATP production; these results were confirmed in tumor cell lines as HeLa and HCT116." (PMID 31947673, 2020). "As a key regulatory factor in tumor metabolic reprogramming, TRAP1 is involved in a variety of mechanisms." (PMID 33575209, 2020). "This TRAP1 function is relevant for its regulation of specific cell functions and for its role in tumor progression." (PMID 33025742, 2020). "Under metabolic stress conditions, particularly nutrient-poor and hypoxic conditions, SDHB regulation with Hsp90/TRAP1-directed protein folding produces sufficient energy to meet the energy metabolism requirements of tumor cells." (PMID 33575209, 2020). "TRAP1 levels are also reduced in metastatic sites compared to the primary tumor, and a downregulation of its expression correlates with epithelial-mesenchymal transition, which in turn indicates chemoresistance." (PMID 32235572, 2020). "TRAP1 is also responsible for reprogramming of tumor bioenergetics as it downregulates oxidative phosphorylation, upon inhibition of succinate dehydrogenase, and enhances Warburg metabolism." (PMID 33065966, 2020). "Mitochondrial TRAP1 is a key regulatory factor involved in metabolic reprogramming in tumor cells that favors the metabolic switch of tumor cells toward the Warburg phenotype." (PMID 33575209, 2020). "This review discusses the molecular mechanisms by which TRAP1 regulates tumor progression, considers its role in apoptosis, and summarizes recent advances in the development of selective, targeted TRAP1 and Hsp90 inhibitors." (PMID 33575209, 2020). "Low TRAP1 expression and high p70S6K expression increase cell motility and promote tumor cell migration." (PMID 33575209, 2020). "TRAP1 regulates the cell cycle to modulate cell proliferation and promotes tumor metastasis by inducing mitochondrial fission." (PMID 33575209, 2020). "Its role in mitochondria suggests that TRAP1 is involved in tumor cell apoptosis to promote tumor progression." (PMID 33575209, 2020). "Our findings provide a tumor-specific approach to suppress cholesterol biosynthesis by targeting TRAP1, which is up-regulated in tumor cells as compared to normal cells." (PMID 31181660, 2019). "TRAP1 knockdown provokes a decrease of mitochondrial aerobic respiration, sensitises cells to lethal stimuli, and inhibits the in vivo tumour growth of both MDA-MB-231 and MCF-7 cells." (PMID 31052256, 2019). "In the context of human CRC, TRAP1 acts as an oncogene and its upregulation is responsible for driving tumor progression and patients’ prognosis." (PMID 31878280, 2019). "That’s why inhibition of TRAP-1 has to be chosen taking into account the potential role in tumor growth or survival." (PMID 35582577, 2019).
tumor (continued). "Inhibition of TRAP1 along with activation of LXR results in synergistic growth reduction of tumor cells in vitro and in vivo." (PMID 31181660, 2019). "TRAP1 is a mitochondrial chaperone and key regulator of mitochondrial bioenergetics in tumor cells (Masgras, Sanchez‐Martin, Colombo, & Rasola, 2017)." (PMID 30680959, 2019). "In particular, TRAP1 seems to modulate tumor energy metabolism by activating glycolysis and repressing OXPHOS, and this function is context- and tumor-specific." (PMID 31163702, 2019). "TRAP1 has been strongly expressed in tumor cells such as breast, colon, pancreas and lung whereas basal expression was detected in corresponding normal cells." (PMID 31540420, 2019). "A significant feature about this finding is that it enables a “tumor specific” approach to interfere with cholesterol synthesis since, as mentioned, the target TRAP1 is increased in tumor cells." (PMID 31181660, 2019). "Previous studies regarding TRAP1 were mainly focused on tumor cells, showing that TRAP1 stays at the crossroad of multiple crucial processes in the initiation of neoplastic transformation and oncogenesis." (PMID 31143823, 2019). "In this model also the mitochondrial chaperone TRAP1 is highly expressed from the initial, pre-neoplastic lesions, and it probably contributes to the anti-oxidant mechanisms of tumor cells by decreasing SDH-generated ROS." (PMID 30197878, 2018). "This mitochondrial network provides high TRAP1-expressing tumor cells the ability to use spare respiratory capacity given limited glucose availability, providing stronger ability to handle metabolic stress." (PMID 29621137, 2018). "The mitochondrial HSP90/TRAP1 network enhances tumor cell invasion during low nutrient and metastatic dissemination." (PMID 29621137, 2018). "The role of TRAP1 is to enhance or suppress oxidative phosphorylation; the effects of such regulation on tumor development and progression are controversial." (PMID 29621137, 2018). "In this review, TRAP1 puzzling functions were recapitulated with a special focus on the correlation between metabolic reprogramming and tumor outcome." (PMID 29621137, 2018). "Compelling evidence suggests a link between TRAP1 antioxidant function and its tumor suppressing activity." (PMID 29621137, 2018). "TRAP1 has an oncogenic activity and its expression is induced in a variety of tumor types; however, TRAP1 levels decrease in the advanced stages of a small set of epithelial cancers." (PMID 30197878, 2018). "Immunohistochemical analysis of human specimens from grade IV revealed that TRAP1 was highly expressed in the tumor cell population." (PMID 29621137, 2018). "This evidence, together with the previous inclusion of TRAP1 in a list of estrogen-regulated genes, prompted us to focus on the correlation between TRAP1 and tumor outcome in gynecological malignancies." (PMID 29621137, 2018). "In future sudies, expressions of TRAP1 in different parts of the same tumor, especially in the front of invasion where it has contact with the microenvironment, need to be determined." (PMID 28088229, 2017). "Accordingly, TRAP1 expression levels inversely correlate with tumor grade in cervical carcinoma, clear cell renal cell carcinoma, and high-grade ovarian cancer." (PMID 28405578, 2017). "From these findings, we suggest that TRAP1 enables tumor cells to invade stromal tissue by epithelial-mesenchymal transition (EMT)." (PMID 28088229, 2017). "In mouse cells, mitochondrial HSP90 and TRAP1 are expressed in tumor cells and in high levels also in testis and brain." (PMID 29290944, 2017). "Eventually, at sacrifice, total tumor burden appeared similar between the two groups, indicating that beyond tumor initiation Trap1 is dispensable for subsequent tumor growth." (PMID 28407697, 2017). "Accordingly, TRAP1 interaction with the Ca2+-binding protein Sorcin was reported to enhance both the stability of the chaperone and resistance of tumor cells to antineoplastic compounds." (PMID 28405578, 2017).
tumor (continued). "In the future, the challenge will be to dissect the functional importance of Hsp90α and Trap1 separately in the tumor cells, in the stroma and in the metastatic niche across a panel of tumor models." (PMID 28407697, 2017). "In the last few years, several observations have pointed toward an important role played by TRAP1 in the adaptive metabolic changes of tumor cell mitochondria." (PMID 28405578, 2017). "In accord with the importance of TRAP1 induction along tumor progression, we have recently observed that its protein levels are markedly increased in very early, pre-neoplastic foci in a model of liver carcinogenesis." (PMID 28405578, 2017). "TRAP1 protects tumor cells from ROS-dependent permeability transition pore opening through deregulated mitochondrion-restricted kinase signaling." (PMID 28088229, 2017). "Such study will help us elucidate the relationship between TRAP1 expression and the tumor microenvironment." (PMID 28088229, 2017). "Another significant protein responsible for succinate elevation is TRAP1, a mitochondrial chaperone which is highly expressed in a series of tumor cells." (PMID 28881853, 2017). "In contrast, in renal cell carcinoma, bladder and cervical cancers, Trap1 protein levels are lower when compared to normal tissue and they display an inverse correlation with tumor stage." (PMID 28407697, 2017). "In the last few years, several reports have demonstrated that TRAP1 is involved in the metabolic regulation of tumor cells." (PMID 28405578, 2017). "Consistent with the earlier elucidation of a TRAP-1 proteome in tumor mitochondria, a key substrate of the proteostasis network identified here was the iron-sulfur SDHB subunit of oxidative phosphorylation Complex II." (PMID 27389535, 2016). "We recently demonstrated that lower expression of the molecular chaperone TRAP1 in OC patients correlates with higher tumor grade and stage, and platinum resistance." (PMID 27977010, 2016). "In some tumor types OXPHOS is also inhibited by increased expression of TRAP1, a mitochondrial molecular chaperone of the Hsp90 family that down-regulates both respiratory complex IV and SDH." (PMID 27070090, 2016). "in accord with a central role played by TRAP1 in energy metabolism of tumor cells, we found that knocking-down TRAP1 increased both basal and maximal oxygen consumption rate of RH cells." (PMID 27070090, 2016). "In this scenario, succinate acts as an oncometabolite, implying that metabolic changes elicited by TRAP1 directly contribute to tumor growth." (PMID 27070090, 2016). "In this study, we have shown that the unfoldase-peptidase ClpXP forms a complex with survivin and the Hsp90-like chaperone TRAP-1 in mitochondria of tumor cells." (PMID 27389535, 2016). "It is worth noting here that TRAP1 upregulation protected scramble and shTRAP1 cells from irinotecan-induced apoptosis, whereas its cytoprotective activity was lost in tumor cell lines silenced for BRAF." (PMID 26084290, 2015). "To further determine the importance of TRAP1 in tumorigenesis, we investigated the effect of TRAP1 knockdown on tumor growth in vivo." (PMID 26517089, 2015). "TRAP1 knockdown substantially inhibited in vivo tumor growth derived from MDA-MB-231 cells and MCF-7 cells." (PMID 26517089, 2015). "Accordingly, this study verifies the concept that inhibition of TRAP1 chaperoning activity represents a strategy for targeting dependency of BRAF-addicted tumor cells on TRAP1 quality control and antiapoptotic pathway." (PMID 26084290, 2015). "Our findings demonstrate that SDH inhibition by TRAP1 is oncogenic not only by inducing pseudohypoxia, but also by protecting tumor cells from oxidative stress." (PMID 25564869, 2014). "We have recently shown that the mitochondrial chaperone TRAP1, which is highly expressed in a variety of tumor cell types, decreases the succinate dehydrogenase (SDH) enzymatic activity of respiratory complex II, thus inhibiting respiration." (PMID 25564869, 2014).
tumor (continued). "This anti-oxidant activity of TRAP1 protects tumor cells from death in conditions of nutrient paucity that mimic those encountered in the neoplasm during the process of malignant accrual, and it is required for in vitro tumorigenic growth." (PMID 25564869, 2014). "TRAP1 is a mitochondrial chaperone highly expressed in many tumor types; it inhibits respiratory complex II, down-modulating its succinate dehydrogenase (SDH) enzymatic activity." (PMID 25564869, 2014). "Our findings place the mitochondrial chaperone TRAP1 at the crossroad of mitochondrial signalling in tumor cells." (PMID 25564869, 2014). "In turn, succinate inhibits the prolyl hydroxylase that primes HIF1α for proteasomal degradation, and HIF1α stabilization is required for tumorigenesis both in vitro and in xenografts of TRAP1-expressing tumor cells." (PMID 25564869, 2014). "Recent results have suggested that TRAP-1 [TNF (tumour necrosis factor) receptor-associated protein 1], a protein of the chaperone family) normally acts as a tumour suppressor by dampening mitochondrial respiration." (PMID 24079832, 2013). "In tumour cells TRAP-1 expression is reduced and triggers enhanced respiration in mouse and human cell lines with a concomitant suppression of aerobic glycolysis." (PMID 24079832, 2013). "Possibly, in tumor cells, the up-regulation of both TRAP-1 in conjunction with HSP90, which both interact with Cyclophilin-40 (CypD) maintains mitochondrial homeostasis and survival of cells." (PMID 20860785, 2010). "Up-regulation of TRAP-1 and HSP90 is therefore directly linked to defined genetic alterations and supports a model of oncogene cooperation in the establishment of this tumor-survival promoting chaperone network." (PMID 20860785, 2010). "Therefore, we used mouse Malignant Peripheral Nerve Sheath Tumor cells (sMPNST cells) where TRAP1 plays a crucial pro-neoplastic role to assess how the different TRAP1 variants tune SDH activity." (PMID 40074754, 2025). "The activity of TRAP1 in tumor models is regulated by post-translational modifications (PTMs)." (PMID 40424720, 2025). "We reasoned that TRAP1 could tune transcription by regulating cell redox equilibrium, as it acts as a ROS scavenger in different tumor types." (PMID 40877908, 2025). "On the same line, TRAP1 could aggregate multimeric protein complexes in tumor cell mitochondria, thus finely tuning whole signaling axes." (PMID 40424720, 2025). "Indeed, in several tumor types, TRAP1 expression correlates with aggressiveness and its ablation or pharmacological inhibition hamper neoplastic growth." (PMID 40424720, 2025). "Additionally, the discovery of specific inhibitors has contributed to our understanding of TRAP1 as a key regulator in tumor energy metabolism." (PMID 38802732, 2024). "Furthermore, it was suggested that TRAP1 expression levels influence mitochondrial architecture of human neuroblastoma cells and tumour metastasis in vivo." (PMID 39210159, 2024). "In addition, TRAP-1 facilitated the pentose phosphate pathway to shunt carbons back to glycolysis or gluconeogenesis, a much-solicited tumor response." (PMID 37165028, 2023). "Furthermore, it has been suggested that TRAP1 is essential for malignant transformation of cells but is dispensable in later stages of tumour development." (PMID 38098505, 2023). "The role of TRAP1 in tumor development is not well understood." (PMID 37508418, 2023). "In vivo, overexpression of TRAP1 in CAFs of HSC3 cell xenografts model inhibited tumor growth." (PMID 38098505, 2023). "For example, the mitochondrial chaperone TRAP-1 is structurally and functionally similar to the Hsp90 family of proteins, which have the potential to switch on alternate pathways for energy production in tumor cells." (PMID 37007005, 2023). "Thus, developing compounds such as CVM-1118 by targeting the binding to TRAP1 will help reduce the succinate accumulation and prevent tumor progression." (PMID 37351538, 2023).
tumor (continued). "TRAP1 can upgrade the tumor cell death threshold and give them resistance to antineoplastic therapy by scavenging harmful ROS and suppressing mitochondrial permeability transition pore (mPTP) cyclophilin D (CypD; PPIF), which is en essential survival mechanism." (PMID 38098505, 2023). "Further evaluation of the leads obtained in this study may provide mechanistic insights into TRAP-1-mediated metabolic regulation in tumor cells." (PMID 37165028, 2023). "The high expression of TRAP1 can affect the cell glycolysis in the tumor microenvironment." (PMID 38098505, 2023). "TRAP1 is highly expressed in mitochondria isolated from tumor cells compared to normal cells." (PMID 35127545, 2022). "Controversially, TRAP1 has alternately been characterized as an oncogene and tumor suppressor, and it has been suggested that TRAP1 is essential for malignant transformation of cells but dispensable at later stages of tumor development." (PMID 35740911, 2022). "While data supporting the importance of TRAP1 are numerous, these findings are challenged by other reports where TRAP1 expression inversely correlates with tumor stage or is seemingly unimpactful in carcinogenesis models in TRAP1 knockout (KO) mice." (PMID 35883436, 2022). "In the past 10 years, TRAP1 has been found to be highly expressed in a variety of neoplasms." (PMID 35883436, 2022). "Moreover, inactivation of TRAP1 by small interfering RNA (siRNA) in tumor cells treated with β-HIVS or VP16 induced the release of cytochrome c, pointing out an important role of TRAP1 in intrinsic apoptotic pathway." (PMID 35127545, 2022). "TRAP1 can promote tumor metastasis by inducing mitochondrial fission." (PMID 36499214, 2022). "Although, all the knowledge about the role of TRAP1 in tumor cells, its role in central nervous system cells, under physiological and pathological conditions, remains largely unknown." (PMID 34829705, 2021). "In vivo, overexpression TRAP1 expression in CAFs suppress tumor growth." (PMID 34906113, 2021). "TRAP1 has a complex effect on both types of cells (healthy and tumour)." (PMID 34769108, 2021). "TRAP1 induction and subsequent shift towards a glycolytic metabolism may lead to rapid proliferation, especially in early tumor development, where cells could still be vulnerable to oxidative stress." (PMID 34831420, 2021). "TRAP1 is also known to affect mitochondrial architecture and dynamics, where TRAP1 knockdown favours mitochondrial fusion, while TRAP1 overexpression induces mitochondrial fission and subsequently enhanced migration in vitro and in tumour metastasis in vivo." (PMID 34769108, 2021). "Taken together, our data indicate that TRAP1 is induced in a HIF1α-dependent way under both hypoxic and pseudo-hypoxic conditions, and its induction has important consequences on the in vivo metabolic rewiring of neoplasms." (PMID 33934112, 2021). "HDCA leads to oxidative stress and apoptosis in vivo tumor models and displays an action that is functionally opposed to that of TRAP1, as it induces both succinate dehydrogenase and the mitochondrial deacetylase sirtuin-3 (SIRT3), which further enhances succinate dehydrogenase activity." (PMID 34829705, 2021). "A pivotal contributor of such metabolic adaptations is the molecular chaperone TRAP1, which binds and regulates the activity of respiratory complexes, thus exerting oncogene/oncosuppressor functions depending on the metabolic phenotype of each tumor type." (PMID 32235572, 2020). "In addition, TRAP1 is involved in dual regulation of the mitochondrial apoptotic pathway and exerts an antiapoptotic effect on tumor cells." (PMID 33575209, 2020). "Hence, TRAP1 participates in the metabolic switch of tumor cells toward aerobic glycolysis, i.e., decreased OXPHOS activity paralleled by enhanced glucose utilization." (PMID 32766157, 2020).